HDLBP (high density lipoprotein binding protein)
Description:
Appears to play a role in cell sterol metabolism. It may function to protect cells from over-accumulation of cholesterol.
Synonyms: HBP; VGL; PRO2900
Tractability: Antibody: its Gene Ontology location is reachable by antibodies, with high confidence. PROTAC: ubiquitination databases record sites on it; its protein half-life has been measured.
Gene: Protein-coding gene on chromosome 2 (241,227,264 to 241,317,061, reverse strand). Ensembl gene ENSG00000115677.
Subcellular location: Cytoplasm; Nucleus
Subcellular location (Human Protein Atlas): Endoplasmic reticulum; Nuclear bodies
Pathways (Reactome):
Disease: Dengue Virus Genome Translation and Replication
Transport of small molecules: HDL clearance
Gene Ontology:
Molecular function: cadherin binding; protein binding; RNA binding; lipid binding; mRNA binding; nucleic acid binding
Biological process: cholesterol metabolic process
Cellular component: endoplasmic reticulum; nuclear body; endoplasmic reticulum membrane; plasma membrane; cytoplasm; nucleus
Genetic constraint (gnomAD): Loss-of-function variants: 23 observed, 115 expected, observed/expected ratio (o/e) 0.2, 90% interval 0.14 to 0.28. The upper end of that interval is the gene's LOEUF score, 0.28, which puts it in group 1 of 6, group 1 being the genes least tolerant of losing a copy. Missense variants: 1,060 observed, 1,627.2 expected, observed/expected ratio (o/e) 0.65, 90% interval 0.62 to 0.69. Synonymous variants: 579 observed, 587.93 expected, observed/expected ratio (o/e) 0.98, 90% interval 0.92 to 1.05.
Homologues: Orthologues: chimpanzee HDLBP (99% identical), mouse Hdlbp (98% identical), rat Hdlbp (98% identical), guinea pig HDLBP (97% identical), macaque HDLBP (97% identical), rabbit HDLBP (97% identical), dog HDLBP (96% identical), pig HDLBP (94% identical), tropical clawed frog hdlbp (84% identical), zebrafish hdlbpa (80% identical), Drosophila melanogaster Dp1 (47% identical), Caenorhabditis elegans vgln-1 (38% identical), and 2 more. Paralogues in human: BICC1 (14% identical), ANKS6 (9% identical).
Diseases named in the same sentence as HDLBP in open-access papers:
HDLBP is named in the same sentence as 20 diseases in open-access papers, as found by Europe PMC text mining. Sharing a sentence is not in itself a finding about the gene and the disease. The quoted sentences say what the papers report.
hepatocellular carcinoma (6 papers, 2016 to 2024). A malignant tumor that arises from hepatocytes. "In other cancer types, hepatocellular carcinoma, for example, HDLBP is proved to act as an anti-apoptotic effect in promoting cell proliferation and tumor growth." (PMID 34335950, 2021). "Hepatocellular carcinoma: Elevated expression of HDLBP, the largest RNA-binding protein, inhibits ferroptosis in HCC cells." (PMID 38072908, 2023). "High-density lipoprotein-binding protein (HDLBP) binds to and stabilizes ferroptosis-associated lncRNA (lncFAL), which mediates an FSP1-dependent anti-ferroptosis in hepatocellular carcinoma (HCC)." (PMID 37714846, 2023). "A previous study showed that lncFAL stabilized by HDLBP, an important transporter that protects cells from overaccumulation of cholesterol, inhibits ferroptosis vulnerability by diminishing Trim69-dependent FSP1 degradation in hepatocellular carcinoma." (PMID 38191842, 2024).
autism (2 papers, 2023 to 2024). Persistent deficits in social interaction and communication and interaction as well as a markedly restricted repertoire of activity and interest as well as repetitive patterns of behavior. "Contrary to other studies where a haploinsufficiency of KIF1A, FARP2, HDLBP, and AGAP1 genes was cited as a possible cause for autism in 30–35% of 2q37DS, in our patients, autistic spectrum disorder was found in just one case." (PMID 36833393, 2023).
small cell lung carcinoma (2 papers, 2021 to 2023). Small cell lung cancer (SCLC) is a highly aggressive malignant neoplasm, accounting for 10-15% of lung cancer cases, characterized byrapid growth, and early metastasis. "Researchers were then interested in the role of HDLBP in small-cell lung cancer." (PMID 37468977, 2023). "A novel small-cell lung cancer biomarker was identified by Cell-SELEX-generated aptamers in 2019, and the target of aptamer C12 was high density lipoprotein binding protein (HDLBP)." (PMID 37468977, 2023).
atherosclerosis (1 paper, 2022). A disease characterized by the build-up of fatty material and calcium deposition in the arterial wall resulting in partial or complete occlusion of the arterial lumen.
bladder (1 paper, 2022). "However, the mechanism of action in bladder cancers of IKZF3 and density lipoprotein-binding protein (HDLbp), which has not been reported, may be a new prospective therapeutic target for immunotherapy in bladder patients and is worthy of further exploration." (PMID 36211821, 2022).
hyperalphalipoproteinemia (1 paper, 2020). An autosomal dominant genetic condition caused by mutation(s) in the CETP gene, encoding cholesteryl ester transfer protein. "The significant decrease of HDLBP which expression is upregulated by intracellular cholesterol loading, thus confirms our earlier suggestion on the decreased level of cholesterol in PBMC at hyperalphalipoproteinemia." (PMID 33269026, 2020).
liver cancer (1 paper, 2021). An epithelial or non-epithelial malignant neoplasm that arises from the liver. "In cancer, upregulation of HDLBP expression, e.g. in liver cancer, has been reported and the protein was proposed to promote proliferation by enhancing G1/S cell cycle transition." (PMID 33829040, 2021).
lung adenocarcinoma (1 paper, 2022). A carcinoma that arises from the lung and is characterized by the presence of malignant glandular epithelial cells. "To test this, we established a CRISPR/Cas9-induced HDLBP KO in the lung adenocarcinoma (LUAD) derived cell line A549." (PMID 35585045, 2022).
lung carcinoma (1 paper, 2022). "Absence of HDLBP results in decreased translation efficiency of HDLBP target mRNAs, impaired protein synthesis and secretion in model cell lines, as well as decreased tumor growth in a lung cancer mouse model." (PMID 35585045, 2022).
myotonic dystrophy type 1 (1 paper, 2020). Steinert disease, also known as myotonic dystrophy type 1, is a muscle disease characterized by myotonia and by multiorgan damage that combines various degrees of muscle weakness, arrhythmia and/or cardiac conduction disorders, cataract, endocrine damage, sleep disorders and baldness. "As expected, we were able to pull down proteins known to bind RNA such as CELF2, HNRNPM, and HDLBP, as well as RBPs involved in muscle diseases such as MBNL1, which plays a key role in the pathogenic mechanism of myotonic dystrophy type 1." (PMID 33338663, 2020).
prostate tumors (1 paper, 2019). "DNAAF2, U2AF1, C1QBP, Snapin, or HDLBP are upregulated in prostate tumors or PCa cell lines." (PMID 31694235, 2019).
tumor (7 papers, 2021 to 2026). "Furthermore, the differential expression of HDLBP phosphosites across multiple cancers was observed using UALCAN, suggesting a potential role for phospho-regulation of HDLBP in tumor-associated pathways." (PMID 41828375, 2026). "The lipid transporter high-density lipoprotein-binding protein (HDLBP) is clinically relevant to tumor metastasis in patients with HCC." (PMID 40351413, 2025). "The HR < 1 downregulation of PTPN6 and IKZF3 is considered a tumor suppressor, while the HR > 1 upregulation of HDLBP and EMC1 is considered an oncogene." (PMID 36211821, 2022). "Collectively, these findings suggested that HDLBP substantially influences the oncogenic properties of tumor cells." (PMID 35585045, 2022). "In the future, further implications of the regulatory role of HDLBP for tumor biology need to be explored." (PMID 35585045, 2022). "In accordance, tumor volume and final tumor mass were significantly reduced by HDLBP deletion, indicating that HDLBP is essentially involved in tumor initiation and growth." (PMID 35585045, 2022). "In sum, the presented findings provide strong evidence that HDLBP is an important modulator of tumor progression influencing the expression of secreted factors, receptors, and extracellular matrix components involved in modulating tumor initiation and progression." (PMID 35585045, 2022). "Strikingly, tumor initiation and growth were severely reduced by HDLBP deletion." (PMID 35585045, 2022). "Finally, the results presented in this study highlight the striking involvement of HDLBP in lung tumor cells during tumor progression and suggest that therapeutic interventions targeting HDLBP may represent a previously unrecognized strategy for inhibiting lung tumor growth or other malignancies." (PMID 35585045, 2022). "The NUP85, HAX1, GNPDA1 and HDLBP protein levels were significantly elevated in tumor tissues compared to normal samples, while GPD1 was significantly down-regulated in tumor tissues." (PMID 33663535, 2021). "HDLBP and EMC1 were upregulated in tumor tissue and correlated with poor survival." (PMID 36211821, 2022). "In the absence of HDLBP, a high number of mRNAs was found to be up (n = 1039) and downregulated (n = 700), suggesting that HDLBP has a great impact on gene expression, presumably due to substantially impaired cell signaling and tumor-stroma cross-talk." (PMID 35585045, 2022). "Finally, we expanded our findings to an in vivo system and evaluated the effect of the absence of HDLBP on tumor formation capacity." (PMID 35585045, 2022). "In addition, NUP85, HAX1, GNPDA1 and HDLBP exhibited elevated mRNA expression levels in GI tumor tissues when compared to the adjacent non-tumor tissues, whereas GPD1 expression was suppressed in GI tumor tissues compared to the non-tumor tissues." (PMID 33663535, 2021).
cancer (6 papers, 2021 to 2026). A tumor composed of atypical neoplastic, often pleomorphic cells that invade other tissues. "In summary, we identified and validated a glycolysis associated five-gene risk signature (NUP85, GPD1, HAX1, GNPDA1 and HDLBP) that can predict the OS of GI Asian cancer patients." (PMID 33663535, 2021). "Although not comprised in any cancer hallmark gene set, we decided to evaluate regulation of HDLBP expression by IGF2BP1 and confirmed that IGF2BP1 promotes HDLBP expression by mRNA stabilization." (PMID 33829040, 2021). "To prove the validity of these in silico evaluations, we validate three novel target mRNAs by demonstrating that IGF2BP1 promotes the expression of AURKA, HDLBP, and YWHAZ in cancer cells by impairing decay of the respective mRNAs." (PMID 33829040, 2021). "Notably, specific mutations were observed in genes involved in lipid localization and transport, including AKR1C1, HDLBP, and ABCC3, suggesting disruptions in lipid metabolism that facilitate the rapid proliferation of cancer cells." (PMID 38010945, 2024).
GI tumor (1 paper, 2021). "We identified five novel glycolysis-associated genes (NUP85, GPD1, HAX1, GNPDA1, and HDLBP) in GI tumor and normal tissues." (PMID 33663535, 2021).
HDLBP also shares sentences with these, for which no sentence is quoted: Obesity (2 papers); autistic spectrum disorder (1); behavioral disorders (1); bladder cancers (1); brachydactyly (1); tauopathy (1).